SOX2 (SRY-box transcription factor 2)
Diseases named in the same sentence as SOX2 in open-access papers (continued):
Sharing a sentence is not in itself a finding about the gene and the disease.
tumor (continued). "We found that tumor tissues from HCT116 cells infected with Sox2 displayed a higher Sox2 protein level compared with tumors from HCT116 cells infected with mock vector." (PMID 23451179, 2013). "Our results show that increased tumor SOX2 levels predict better outcome in NSCLC and the effect is independent of histologic type." (PMID 23620753, 2013). "In the Yale cohort, cases with high tumor SOX2 levels (n = 173) showed higher median survival compared to the low SOX2 expressers (median survival, not reached vs. 39 months respectively, log rank p = 0.0113)." (PMID 23620753, 2013). "Several recent studies have identified the important roles of Nanog, Sox2 and Oct3/4, which are involved in reprogramming and maintenance of stem cell function, in tumour aggressiveness." (PMID 22433967, 2012). "A combined genomic analysis of the Oct-4/SOX2/NANOG pathway has recently demonstrated high prognostic accuracy in studies of patients with multiple tumor types." (PMID 22300949, 2012). "The tumor suppressor p27Kip1 has an unexpected role in direct transcriptional regulation of Sox2 during the differentiation of pluripotent cells." (PMID 23217425, 2012). "This was further strengthened by in situ hybridization on mouse brains revealing that the expression pattern of miR-21 was specific to tumor areas and strongly overlapped with areas staining positive for SOX2." (PMID 22931209, 2012). "To confirm that our BTIC cultures derived from the surgically resected GBM tissues were indeed concentrated in tumor stem cells, we performed immunoblotting assays using antibodies directed against two well known stem cell markers, nestin and Sox-2." (PMID 23110111, 2012). "Two recent reports demonstrate that ectopic expression of Sox2 increased the frequency of side population cells and tumor formation in mouse and human NSCLC cell lines." (PMID 23009336, 2012). "Transcription factors that have been shown to maintain the pluripotency and self-renewal of ES cells and tumor cells include Oct4, Nanog, Sox2, Rex1 and Sall4." (PMID 23049777, 2012). "We also showed that, in vitro, UTF1 expression is not restricted to SC and that it is localized in the nucleus of somatic tumor cells independently of Oct4A and Sox2 expression." (PMID 22880087, 2012). "In accordance with RT-PCR results, Western blot analysis showed that the protein expressions of Oct-4 and Sox-2 were up-regulated in the CD133+ tumor spheroid-forming subpopulation, while the protein level of Nanog was not increased." (PMID 22643117, 2012). "Consistent with the previously reported study, BTICs derived from GBMs highly expressed nestin and Sox-2 compared to differentiated cultures derived from the same tumor tissues." (PMID 23110111, 2012). "Our data show that miR-21 and SOX2 are tightly regulated already during embryogenesis and define a distinct population with putative tumor cell of origin characteristics." (PMID 22931209, 2012). "The correlation between the expression of Sox2 and Oct4 and tumor type, grade, prognosis and the utility of the two genes in discriminating between benign and malignant tumors was analyzed as well." (PMID 22837720, 2012). "We showed by a gelatin zymography assay that the MMP2 activity was down regulated after SOX2 knocked down, suggesting it is one of the mediators for the SOX2 effect on cell invasion/migration, and tumor metastasis." (PMID 22912670, 2012). "Compared to the primary site tumor for stage IV patients, higher numbers of metastasized tumors were positive for Sox2." (PMID 23009336, 2012). "It showed that the previously observed overlap of miR-21 and SOX2 expression was even more pronounced, exhibiting a total overlap in the tumor area." (PMID 22931209, 2012). "In the composite tumor, the three components expressed SOX2, but CDX2 was expressed in the neuroendocrine component." (PMID 22482081, 2012).
tumor (continued). "Expression of stem cell transcription factor SOX2 was consistently detected in a tumor cell sub-population in primary NPC and is believed to be a potential marker for NPC CSCs." (PMID 23285037, 2012). "In an important connection to these findings, SOX2 overexpression has been reported recently in many aggressive tumors, including tumors of the breast, lung, prostate and brain." (PMID 22937156, 2012). "The correlation between the expression of Sox2 and Oct4 and tumor type, grade and prognosis and the utility of the two genes in discriminating between benign and malignant tumors were analyzed as well." (PMID 22837720, 2012). "In this study, for the first time, we have documented a high Sox2 expression in GCSCs and shown its pivotal role in chemotherapy resistance and tumor growth." (PMID 23554769, 2012). "Conversely, others isolated and then studied tumor cells that stably express elevated levels of SOX2 (∼3- to 4-fold) from a drug selected transgene." (PMID 22937156, 2012). "It is thus possible that SOX2 can cooperate with these important oncogenes to promote tumor occurrence." (PMID 22615765, 2012). "We found that RNAi-mediated inhibition of PLK1 mRNA in tumor spheres significantly decreased SOX2 mRNA expression compared to control transfected cells with no significant change in NES, Nanog, and c-Myc mRNA expression." (PMID 22390279, 2012). "Understanding how SOX2 levels are carefully controlled in tumor cells will provide novel insights into the fundamental biology of these cancers." (PMID 22937156, 2012). "The CSC cultures contained 74.8 percent Sox2 positive cells (i.e. in vitro) as compared to 24.9 percent of Sox2 positive YFP cells (CSC derived) within the tumor (i.e. in vivo)." (PMID 21961046, 2011). "In both experiments, increased expression of E-cadherin was observed, which suggests that both Twist1 and Sox2 function in harmony and that their concurrence is essential for the maintenance of tumor plasticity." (PMID 22184289, 2011). "We detected high Sox2 and Twist1 expression levels in these samples with differential expression in non-tumor areas, suggesting their expression in cancerous tissues and not in normal brain tissue." (PMID 22184289, 2011). "The data indicate that tumour foci on the lung surface of mice or lung weights of mice implanted with D121-SP SOX2 knock down cells are significantly smaller than that in mice implanted with wild-type D121-SP cells (P<0.001)." (PMID 21468047, 2011). "A trend to larger tumor size (p = 0.073) and to a histology other than of ductal or lobular type was noted in SOX2 expressors (p = 0.053)." (PMID 21276239, 2011). "We performed realtime PCR to assess gene transcript levels for Oct4, Nanog, and Sox2, as well as mouse telomerase reverse transcriptase (mTRET), a catalytic subunit of telomerase, in CD44hi and CD44neg tumor cells." (PMID 21858056, 2011). "Using specific antibodies against Sox2, Oct4 and Nanog we found an extensive overlap in their expression pattern and many grade IV tumor cells expressing Nanog or Oct4 protein co-expressed Sox2." (PMID 21483788, 2011). "To further explore SOX2 function in the SP of D121 tumour cells, we applied the siRNA technology to knockdown SOX2 gene expression." (PMID 21468047, 2011). "Expression of SOX2 correlated significantly with lymph node metastases (p = 0.006), distant metastases (p = 0.022) and histopathological tumour grade (p = 0.043) according to WHO." (PMID 22168803, 2011). "Interesting findings include that SOX2 regulates the expression of SOX family proteins SOX1 and SOX18, and that SOX2 down regulates BEX1 (brain expressed X-linked 1) and BEX2 (brain expressed X-linked 2), two genes with tumor suppressor activity in GBM." (PMID 21211035, 2011). "The tumor cells homogeneously expressed nuclear SOX2, and most of them were cycling, as assessed by Ki67 staining." (PMID 20126410, 2010).
tumor (continued). "Positive staining for Oct4 and Sox2, mainly localized in the nucleus, were observed in the cancer cells of tumor tissues." (PMID 20937145, 2010). "Lin28B inhibited accumulation of mature let-7, which resulted in the increased expression of Sox2, Nanog and Oct4, leading to increased self-renewal and tumor growth." (PMID 20805998, 2010). "First, SOX2 is capable of transforming and conferring tumor-initiating properties to human lung squamous cells, as we demonstrated." (PMID 20126410, 2010). "A possible explanation for this relatively mild transforming power is that additional hits are required downstream or in cooperation with SOX2 activation and that a specific genetic makeup is required in the tumor to fully allow for SOX2 oncogenic action." (PMID 20126410, 2010). "The expression of SOX2 in different normal tissues and tumour specimens was thoroughly quantified with a sensitive real-time PCR method." (PMID 17375044, 2007). "When investigating the suitability of SOX2 to serve as a target antigen for T cells, we identified an immunogenic HLA-A*0201-restricted peptide derived from SOX2, which proved to be effective in activating tumour-directed CTL responses." (PMID 17375044, 2007). "In 80% of the tumour specimens (8 out of 10), SOX2 was overexpressed by more than five-fold, and in 40% of the samples (4 out of 10), SOX2 was upregulated 20-fold or higher." (PMID 17375044, 2007). "SOX2 in combination with CD34 have been proposed to mark ‘tumour initiating cells’ in cSCC33." (PMID 41507151, 2026). "Moreover these tumours expressed the stem-cell marker CD34 which together with SOX2 have been proposed to mark a population of ‘tumour initiating cells’33." (PMID 41507151, 2026). "Furthermore, SOX2 is commonly used as a marker of cancer stem cells and is upregulated in ~20% of cSCC patients, where it rewires cells for tumour initiation and growth." (PMID 41507151, 2026). "Additionally, SOX2 promotes tumor cell proliferation and survival by upregulating cyclin D1 and activating the Wnt/β-catenin pathway, contributing to aggressive tumor behavior in NSCLC." (PMID 41268614, 2026). "Consistently, spatial transcriptome and mIHC analyses using adjacent sections show that TLS regions containing MIF+ tumor cells (SOX2+) are enriched with exhausted T cells (CD3+PD-1+TIM-3+) and exhausted B cells (CD20+CD21-CD27-PD-1+), indicating an impaired B-cell immune response." (PMID 41355948, 2026). "Conversely, loss of SOX2 in the IVL+ tumour-resistant population further prevented tumour onset and growth upon oncogene expression, while it did not affect the K5/K14+ tumour-primed population." (PMID 41507151, 2026). "Depletion of Tregs or inhibition of the SOX2 pathway restores T cell infiltration and markedly suppresses tumor growth, suggesting that targeting the SOX2 pathway may synergistically enhance the therapeutic efficacy of ICIs." (PMID 41268614, 2026). "Using expression and transcriptomic studies, we demonstrate the presence of SOX2/SOX2-expressing cells across a broad range of PCCs and PGLs, irrespective of tumour aggressiveness, location, and causative mutation." (PMID 42023823, 2026). "Additionally, SOX2 has been shown to promote proliferation and tumor growth in a variety of cancer entities." (PMID 41129070, 2026). "Importantly, overexpression of SOX2 in the IVL+ tumour-resistant population overrode the activation of the apoptotic programme, marked by the expression of activated cleaved CASP3 and PARP seen before in the Ivl:BRAFV600E model." (PMID 41507151, 2026).
tumor (continued). "The percentage of Ki-67–positive tumor cells was also comparable between groups, indicating that SOX2 loss does not impair proliferative capacity." (PMID 41266112, 2026). "Interestingly, the slow-growing Ivl:BRAFV600E-SOX2fl/fl tumours show patches escaping recombination and retaining SOX2 protein expression, as demonstrated by IHC, which highlights its critical role in tumorigenesis in this model." (PMID 41507151, 2026). "Nevertheless, SOX2 rendered this population permissive to tumorigenesis, preventing delamination and reducing apoptosis, by inducing a stem-like transcriptional state that mirrors the tumour-primed K14/K5+ population." (PMID 41507151, 2026). "On the other hand, SOX2 may also affect the tumor microenvironment, as it has been reported to regulate neutrophil recruitment via chemokines and metabolism by enhanced expression of the glucose transporter GLUT1 in SCCs." (PMID 39455281, 2025). "SOX2 functions in the molecular signature of tumor cells were investigated." (PMID 40128799, 2025). "Experiments have confirmed that knockdown of PHF20L1 or LSD1 in PA-1 cells and mouse ESCs leads to the loss of SOX2 protein stability and significantly impairs the self-renewal capacity of stem cells, which provides a new molecular basis for therapeutic strategies targeting SOX2-positive tumours." (PMID 40723918, 2025). "Sox2 knockdown resulted in significantly reduced Ki-67 expression in tumor cells." (PMID 40128799, 2025). "SOX2 inactivation attenuated progenitor-like features and blunted tumor growth." (PMID 40128799, 2025). "We utilized the EBC2 lung SCC xenograft model to assess whether pCRISPRi targeting ΔNp63 or SOX2 suppresses tumor growth in vivo." (PMID 40871074, 2025). "We postulated that potential SOX2 transcriptional targets should be elevated in tumor cells." (PMID 40128799, 2025). "The discrepancy between in vitro and in vivo SOX2 mRNA repression might be explained by differences such as transcriptional kinetics and the tumor microenvironment." (PMID 40871074, 2025). "For example, it has been reported by other groups that, in mice bearing either combined Braf CA/+PtenΔ/Δ53 or NrasQ61K/+Ink4aΔ/Δ54 mutations, loss of Sox2 did not prevent tumor formation." (PMID 40571713, 2025). "In conclusion, we identified a critical role for AKT in promoting SOX2 overexpression, tumor stemness, and chemoresistance in OS, and provided evidence that targeting AKT combined with chemotherapy may hold promise for treating refractory OS." (PMID 39994220, 2025). "Then, the tumor cells were analyzed for gene editing percentages in the SOX2 knockout." (PMID 39736115, 2025). "These disparities demonstrate how variations in cutoff criteria and tumor context may influence SOX2’s prognostic relevance, stressing the importance of standardizing scoring techniques in OSCC research." (PMID 40227667, 2025). "The role of SOX2 in tumor progression appears contextdependent." (PMID 41426972, 2025). "SRY-box transcription factor 2 (SOX2), a core transcription factor that maintains the pluripotency of embryonic stem cells (ESCs), is closely associated with the acquisition of tumour stem cell-like characteristics and metastasis when its expression is dysregulated." (PMID 40723918, 2025). "Tumor (SOX2+) and TAM (IBA1+) segments were selected for targeted spatial analysis." (PMID 40960500, 2025). "Experimental results from PCa cells with either overexpression or knockdown of SOX2 suggest that directly targeting the SOX2 transcription factor could be a promising strategy for inhibiting tumor initiation and progression." (PMID 40821114, 2025).
tumor (continued). "Additionally, adenosylmethionine decarboxylase 1 (Amd1) upregulates Sry-box transcription factor 2 (Sox2), Kruppel-like factor 4 (Klf4), and Nanog through Fto-mediated mRNA demethylation, maintaining tumor stemness." (PMID 41208876, 2025). "Furthermore, ALKBH5 downregulation significantly decreased expression of SOX2 and the tumor sphere formation frequency of GBM stem‐like cells (GSCs) derived from NFHDCD cells (NFHDCD‐GSCs)." (PMID 39974663, 2025). "SOX2 plays a significant role in regulating tumor initiation and stem cell function." (PMID 39781447, 2025). "SOX2 is a reliable marker for tumor stem cells (TSCs) within benign odontogenic lesions." (PMID 41176605, 2025). "First, epigenetic changes could activate other stem cell‐related genes, enabling the tumor cells to compensate for the SOX2 inhibition." (PMID 39736115, 2025). "Ki-67 (Proliferation): SOX2 and PIWI expression levels showed a strong positive correlation with Ki-67 staining across all cancer types (r = 0.65–0.72, p < 0.001), highlighting their association with tumor cell proliferation and aggressive behavior." (PMID 40674376, 2025). "Also in the lung, it was shown that SOX2 expression influences the tumor immune microenvironment (TIME) and the infiltration of tumor-associated neutrophils (TANs)." (PMID 40643470, 2025). "Thus, SOX2 presents both an adverse role in facilitating tumor growth and a positive aspect concerning treatment efficacy." (PMID 39976818, 2025). "However, SOX2 silencing or erlotinib treatment significantly reversed TGIF2 overexpression-promoted increase in tumor size (TGIF2-OE vs. TGIF2-OE/shSOX2; TGIF2-OE vs TGIF2-OE/Erlotinib)." (PMID 39781447, 2025). "Numerous studies have demonstrated that SOX2 overexpression contributes to cancer pathogenesis and progression, including cancer cell proliferation, metastasis, tumor initiation, and cancer stem cell function in various tumors, such as lung and esophageal squamous cell carcinomas." (PMID 39994220, 2025). "This combination of abnormal proliferation and differentiation defects indicates that SOX2 + cells may serve as the tumor-initiating cells for PCP." (PMID 40696244, 2025). "Furthermore, we have identified the upregulation of SOX2 as a potentially critical mechanism downstream of SOX9 loss, likely contributing to the observed EMT changes, CSC phenotypes, and tumor progression." (PMID 40179020, 2025). "Interestingly, IHC studies of the matching primary tumor samples revealed SOX2 presence only in the samples from patients who also had SOX2 + CTC clusters, suggesting that CSCs marker expression occurred early in cancer progression." (PMID 40918157, 2025). "Importantly, we provide histopathological validation of this mechanism through autopsy findings showing perivascular infiltration by SOX2-positive tumor cells." (PMID 41510293, 2025). "Minichromosome Maintenance Complex Component 10 (MCM10), overexpressed 4.2-fold in resistant tumors, activates Aldehyde Dehydrogenase 1 Family Member A1(ALDH1A1) and SRY-Box Transcription Factor 2 (SOX2) to promote stemness, evidenced by tumor sphere enlargement." (PMID 40977684, 2025). "The SOX2 suppressed group had a higher prevalence of MSI high cancers (30.9% versus 10%) and of cases with high tumor mutation burden (35% versus 12.4%) than cancers with a SOX2 maintained expression, which presented more frequently high Chromosomal Instability (CIN)." (PMID 40149431, 2025). "However, due to tumor cell heterogeneity, SOX2 exerts stemness-regulating effects in certain PCa cell lines." (PMID 40821114, 2025). "Additionally, IHC analysis of tumour tissues from nude mice revealed that USP18 knockdown resulted in reduced expression of stemness markers (SOX2 and CD133) and a proliferation marker (KI67)." (PMID 40374599, 2025). "SOX2 may have tumor-suppressive functions in the glandular stomach, given that its loss in the antrum derepresses intestinal/metaplastic genes and enhances Wnt-driven tumorigenesis." (PMID 40587339, 2025).